PRL (prolactin)
Diseases named in the same sentence as PRL in open-access papers (continued):
Sharing a sentence is not in itself a finding about the gene and the disease.
cervical cancer (continued). "Our data suggests that PRL/PRLR signaling could act as an important survival factor for cervical cancer." (PMID 24148306, 2013). "More studies are necessary to determine the signaling pathways activated by PRL and could support the transformation mechanisms activated in those cell lines and hence in cervical cancer." (PMID 24148306, 2013). "However, we did find that treatment with PRL had a protective effect against cell death induced by etoposide, decreasing the number of apoptotic cells in all the cervical cancer cell lines." (PMID 24148306, 2013). "To test whether PRL had an effect on the proliferation in cervical cancer cells, we cultured cells in the absence and presence of PRL, PRLR-AB or PRL-AB for 3 and 5 days." (PMID 24148306, 2013). "Furthermore, we showed an autocrine PRL synthesis in cervical cancer cells through the PRL transcript and protein." (PMID 24148306, 2013). "The first evidence indicating the role of PRL in cervical carcinogenesis came from the 1970 decade, where a study determined that PRL enhanced the proliferation of normal neonatal uterine cervix cultured cells from mice and in 3-methylcholanthrene-induced cervical carcinomas." (PMID 34745013, 2021). "For this reason, the purpose of this study was to evaluate the signaling pathways involved in the antiapoptotic effect mediated by PRL/PRLR in cervical cancer, as well as the induction of antiapoptotic genes that could be subserving the development of the carcinogenic process." (PMID 26346346, 2015). "In addition, PRL augmented cell proliferation in HeLa cells and had a protective effect against etoposide induced apoptosis in HeLa, SiHa and C-33A, suggesting that PRL/PRLR signaling could act as an important survival factor for cervical cancer." (PMID 24148306, 2013). "The aim of this study was to evaluate the expression of PRL/PRLR and the effect of PRL treatment on cell proliferation and apoptosis in cervical cancer cell lines." (PMID 24148306, 2013). "In the present study, we determined the expression levels of PRL and PRLR and the effect of PRL treatment on cell proliferation and apoptosis in HeLa, SiHa and C-33A cervical cancer cell lines." (PMID 24148306, 2013). "With this background information, we decided to evaluate the expression levels of PRL and PRLR and their possible participation in cell survival of cervical cancer cell lines." (PMID 24148306, 2013). "Worth to note, the potential direct effects of dopamine agonists on PRL synthesis and release in cervical cancers has not been clearly investigated." (PMID 33162942, 2020). "Cytoplasmic staining for PRL was positive in 45% of cervical carcinoma tissue sections and in none of the surrounding normal cervix tissue." (PMID 33162942, 2020). "The results showed that the increment in the PRL-mediated phosphorylation of STAT3 in the cell lines HeLa, SiHa and C-33 A was detectable 48 h after treatment and that co-stimulation with the AG490 reduced this effect in the three cervical cancer cell lines." (PMID 26346346, 2015). "There are few reports that have focused on the analysis of the PRL or PRLR expression and its possible role in cervical cancer remains unknown." (PMID 24148306, 2013). "PRL and PRLR co-expression observed in cervical cancer cells suggests the existence of an autocrine–paracrine loop of action supporting the cell growth in cervical cancer." (PMID 24148306, 2013). "The optical density measurements from western immunoblots showed augmented PRL expression in cervical cancer cell lines in comparison with the non-tumorigenic HaCaT cell line." (PMID 24148306, 2013). "Our findings suggest that PRL could be modulating the induction of antiapoptotic genes through STAT3 activation in cervical cancer cells, without discarding the involvement of other alternate routes to those discussed in this paper." (PMID 26346346, 2015).
cervical cancer (continued). "In addition, we reported that PRL and PRLR induction is associated with cell survival, mainly by inhibition of apoptosis, but not by inducing proliferation, in cervical cancer cell lines." (PMID 26346346, 2015). "Treatment with PRL (200 ng/ml) increased cell proliferation in HeLa cells determined by the MTT assay at day 3 and after 1 day a protective effect against etoposide induced apoptosis in HeLa, SiHa and C-33A cervical cancer cell lines analyzed by the TUNEL assay." (PMID 24148306, 2013). "Hence, PRLR expression in cervical cancer has not been well documented and the roles of PRL and PRLR in tumor development are still unknown." (PMID 24148306, 2013).
chronic myeloid leukemia (10 papers, 2016 to 2026). "The results showed that miR-221/222-3p was significantly correlated with chronic myeloid leukemia, central carbon metabolism in cancer, non-small cell lung cancer, apoptosis, and the prolactin signalling pathway." (PMID 41602427, 2026). "Results of KEGG analysis were significantly enriched in the natural killer cell-mediated cytotoxicity, African trypanosomiasis, Fc epsilon RI signaling pathway, prolactin signaling pathway, and chronic myeloid leukemia." (PMID 35386197, 2022).
Cirrhosis (10 papers, 2013 to 2025). A chronic disorder of the liver in which liver tissue becomes scarred and is partially replaced by regenerative nodules and fibrotic tissue resulting in loss of liver function. "ROC curve analysis in this study revealed an AUC of 0.944 (p < 0.001) for serum prolactin as a predictor of severe cirrhosis (CTP Class C)." (PMID 39925608, 2025). "Low testosterone and high prolactin levels were determined to be correlated with the severity of cirrhosis." (PMID 27785243, 2013). "In cirrhosis, excess production of SHBG in liver and increased prolactin levels were detected while exploring the cause of gynecomastia and high level of liver estrogen receptors was added to the direct suppressing effect of estrogen on Leydig cell functions." (PMID 27785243, 2013). "Laboratory values for mean LH, FSH, and prolactin were not significantly different between cirrhosis patients and controls (p>0.05)." (PMID 36814749, 2023). "Moreover, CXCL9 and Prolactin resulted to be correlated with the transaminases (AST and ALT), thus confirming that these proteins can be considered as predictors of inflammatory activation during the progression of T2D and HCV-related cirrhosis, which leads to the cancer." (PMID 26226632, 2015).
diabetes insipidus (10 papers, 2019 to 2025). A disorder characterized by excretion of large amounts of urine, accompanied by excessive thirst. "No cases of precocious puberty, 5 cases of low prolactin level, no cases of corticotropic insufficiency (cortisol peak <500 nmol/l) and no cases diabetes insipidus were recorded." (PMID 30941101, 2019).
leiomyoma (10 papers, 2013 to 2025). A well-circumscribed benign smooth muscle neoplasm characterized by the presence of spindle cells with cigar-shaped nuclei, interlacing fascicles, and a whorled pattern. "We compared the biochemical characteristics like prolactin, luteinizing hormone (LH), estradiol, progesterone, and total cholesterol in leiomyoma patients to examine the influence of MED12 mutations on clinical and biochemical characteristics." (PMID 30619444, 2018). "Regarding the association analysis, a significant positive correlation in groups (+ve and −ve for MED12 mutations) between leiomyoma size with BMI, and prolactin (p for all tests is < 0.05) were observed." (PMID 30619444, 2018). "Among hormonal mediators, hCG plays a key role, stimulating proliferation both directly through hCG receptors on leiomyomas and indirectly via prolactin-mediated pathways." (PMID 41227072, 2025). "Our data also indicated an upregulation of PRL in leiomyomas which is in line with prior reports and a potential mechanism for MAPK activation in leiomyomas." (PMID 35641855, 2022). "PRL, the associated protein-coding gene of CASC15, is one of the most highly expressed genes in leiomyomas." (PMID 35641855, 2022). "Human myometrium and leiomyoma synthetize and secrete prolactin but leiomyomas have been shown to secrete larger amounts of prolactin in vitro than normal myometrial tissue." (PMID 28930160, 2017). "Prolactin-secreting leiomyomas are rare, with only eight cases reported in the literature." (PMID 34540295, 2021). "Moreover, upon binding to the receptor, hCG stimulates prolactin secretion in leiomyoma cells, promoting cell proliferation via the mitogen-activated protein kinase cascade." (PMID 28930160, 2017). "Prolactin secretion can be stimulated by hCG treatment of leiomyoma cultures." (PMID 28930160, 2017). "Prolactin was one of the most up-regulated genes in leiomyomas with HMGA2 rearrangements, MED12 mutations and COL4A5-COL4A6 deletion supporting its role as a mitogenic autocrine growth factor in human leiomyoma tumorigenesis." (PMID 28930160, 2017). "PRL activated MAPK and STAT5 signaling in human myometrial cell lines and promoted myofibroblast trans-differentiation which in turn contributed to leiomyomas fibrosis." (PMID 35641855, 2022). "Our findings implicate SE-lncRNAs in leiomyoma tumorigenesis and progression through the regulation of potential downstream target genes which are in close proximity to their transcription sites (e.g., SOCS2, CBX4, HOXA11, PRL, SPARC, and EGFLAM)." (PMID 35641855, 2022). "However, in our hands PRL is not a strong mitogenic factor by itself and this seems to be the case also in our previous studies concerning glioblastoma and leiomyoma cells." (PMID 34358244, 2021).
Miscarriage (10 papers, 2012 to 2025). A pregnancy that ends at a stage in which the fetus is incapable of surviving on its own, defined as the spontaneous loss of a fetus before the 22th week of pregnancy. "Despite its importance, elevated maternal PRL levels have been linked to implantation failure, miscarriage, and preterm birth, however, the underlying mechanisms for these outcomes remain poorly understood." (PMID 39763651, 2024). "High serum prolactin is associated with miscarriage in humans and prolactin is involved in the T-cell functions associated with maintenance of fetal tolerance." (PMID 22470490, 2012). "Likewise, miscarriage resulted from impaired progesterone synthesis, an endocrine defect in turn associated with ovarian resistance to the gonadotropic effects of prolactin." (PMID 34444016, 2021). "Impaired decidualization, measured by a reduction in the decidualization marker prolactin (PRL) in the endometrium, has been associated with recurrent miscarriage." (PMID 30620718, 2019). "In addition, elevated PRL levels and gram-negative bacteria that produce LPS have both been independently linked to miscarriage and adverse pregnancy outcomes." (PMID 39763651, 2024). "The dNK cell from miscarriage cases also secrete higher level of TNF-α, which inhibits ESCs decidualization by decreasing the decidual markers prolactin (PRL) and insulin-like growth factor binding protein-1(IGFBP-1)." (PMID 34512661, 2021). "Our study found that SGK1 and its signaling pathway-related proteins (p-Nedd4-2, 14–3-3 protein, ENaC-α), estrogen and progesterone and their receptors (E2, P, ERβ, PR), and decidualization markers (PRL, PRLR, IGFBP-1) were expressed at lower levels in unexplained recurrent miscarriage tissue." (PMID 37280474, 2023).
prediabetes (10 papers, 2020 to 2026). "Given the essential role of the adipose tissue in maintaining glucose and lipid homeostasis, PRL may mediate the association between maintaining breastfeeding and lower risks of prediabetes and MetS." (PMID 38610024, 2024). "The women with PCOS categorized as overweight/obese (47.1%), insulin resistant (68.8%), having impaired fasting glycaemia (28.7%) and prediabetes (36.3%) showed significantly higher levels of prolactin compared to the respective counterparts." (PMID 40362476, 2025). "The obtained results are in line with previous observations of our research team, indicating that AT mitigated the inhibitory effect of metformin on prolactin and gonadotropin secretion by overactive pituitary cells in patients with prediabetes." (PMID 39852352, 2025). "They had significantly higher prolactin levels than their counterparts without prediabetes (n = 100, 63.7%)." (PMID 40362476, 2025). "Therefore, we wanted to evaluate the prolactin levels according to the presence of IFG, IGT and prediabetes (defined as IFG and/or IGT)." (PMID 40362476, 2025). "Abnormalities in the lipid profile, insulin resistance, prediabetes or T2DM, MetS, and MASLD could be diagnosed in any patient with low PRL levels, independently by gender." (PMID 39172174, 2024).
renal cell carcinoma (10 papers, 2021 to 2025). "The result of KEGG pathway enrichment indicated that DEGs were significantly enriched in epithelial cell signaling following Helicobacter pylori infection, renal cell carcinoma, malaria, measles, and prolactin signaling pathway." (PMID 35711934, 2022). "KEGG pathway analysis identified 16 significantly enriched pathways such as JAK-STAT signaling pathway, renal cell carcinoma, and prolactin signaling pathway." (PMID 35903364, 2022).
Stroke (10 papers, 2019 to 2024). Sudden impairment of blood flow to a part of the brain due to occlusion or rupture of an artery to the brain. "S100A12 associated with Eotaxin, EGFR, MMP4 and prolactin showed good accuracy in the diagnosis of stroke." (PMID 37511304, 2023). "However, prolactin have been reported to play protective effects on pathogenic or brain dysfunction in various cell and animal models, such as different stroke types, traumatic brain injury, and age-related neurodegenerative diseases." (PMID 37542223, 2023). "While translating our findings into therapeutic interventions remains a challenge, intranasal administration of PRL has shown promising results in neuroprotection in stroke models." (PMID 39499702, 2024). "Since heat-sensitization responses were observed closely relating to curative effect of moxibustion exercise, it could be inferred that LTP in PrL is a key role in the recovery of neurological function for stroke rats." (PMID 31428178, 2019). "We measured urinary epinephrine (E), noradrenaline (NE), dopamine (DA) and cortisol (F) on days 1, 3, and 5 after stroke onset and plasma F, adrenocorticotropic hormone (ACTH), thyrotropin (TSH), prolactin (PRL), follicle-stimulating hormone (FSH), luteinizing hormone (LH) and growth hormone (GH)." (PMID 35968302, 2022).
hyperthyroidism (9 papers, 2019 to 2025). Overactivity of the thyroid gland resulting in overproduction of thyroid hormone and increased metabolic rate. "In prolactinoma and active hyperthyroidism, the prolactin response to the TRH stimulation test is significantly blunted." (PMID 39037546, 2024). "In hyperthyroidism, the prolactin secretion from the pituitary is inhibited, while the serum prolactin level is increased." (PMID 35269847, 2022). "TAs may present with isolated TSH elevation and consequent hyperthyroidism, but in around 40% of cases co-secretion of other hormones predominantly growth hormone (GH) and prolactin (PRL)." (PMID 37117845, 2023). "A study examining the effect of experimentally-induced hyperthyroidism on reproductive dysfunction and gonadotropin secretion in female rats reported decreased serum TSH, FSH, and PRL concentrations, as well as pituitary FSHβ and TSH gene expression levels, in hyperthyroid animals." (PMID 40610792, 2025).
lymphoma (9 papers, 2003 to 2025). A malignant (clonal) proliferation of B- lymphocytes or T- lymphocytes which involves the lymph nodes, bone marrow and/or extranodal sites. "By contrast, neither of these mechanisms has yet been implicated in the regulation of the PIM1 gene, although prolactin activates its transcription in a lymphoma model through several proximal upstream promoter elements, and also requires activation of the Akt kinase." (PMID 22413002, 2012). "One of the less known effects of PRL is the ability to inhibit apoptosis in various cell types, including the Nb2 rat lymphoma cell line." (PMID 12698200, 2003). "The rationale for selecting Jurkat cells, instead of PRL-dependent Nb-2 rat lymphoma cell line, was to have a human model system previously shown to be PRL sensitive." (PMID 12698200, 2003). "Prolactin has been shown to activate the PI3K/Akt/mTOR pathway in a dose‐ and time‐dependent manner in lymphoma models." (PMID 41322031, 2025). "However, the consequences of the local and systemic overproduction of PRL in lymphomas are unknown." (PMID 36941341, 2023). "PRL can also suppress apoptosis in a range of types of cells, such as the Nb2 rat lymphoma cell line, although this property has not been widely addressed." (PMID 36574386, 2022).
Osteopenia (9 papers, 2009 to 2025). Osteopenia is a term to define bone density that is not normal but also not as low as osteoporosis. "Regarding osteopenia in schizophrenic patients, antipsychotic agents are thought to affect the BMD via the inhibition of hypothalamic endocrine caused by the chronic elevation of PRL." (PMID 29079989, 2017). "However, patients with higher PRL levels had a lower incidence of osteopenia." (PMID 37182163, 2023). "In particular, drug-induced prolactin (PRL) production is thought to reduce the sex steroid hormone production via a negative feedback cascade, resulting in osteopenia." (PMID 29079989, 2017).